GPX2 (glutathione peroxidase 2)
Description:
Catalyzes the reduction of hydroperoxides in a glutathione-dependent manner thus regulating cellular redox homeostasis. Can reduce small soluble hydroperoxides such as H2O2, cumene hydroperoxide and tert-butyl hydroperoxide, as well as several fatty acid-derived hydroperoxides. Cannot reduce phosphatidycholine hydroperoxide.
Synonyms: GPx-2; GSHPx-2; GPx-GI; GSHPx-GI; GPRP-2; GI-GPx; GPRP
Tractability: PROTAC: ubiquitination databases record sites on it.
Gene: Protein-coding gene on chromosome 14 (64,939,152 to 64,942,746, reverse strand). Ensembl gene ENSG00000176153.
Subcellular location: Cytoplasm, cytosol
Subcellular location (Human Protein Atlas): Cytosol; Cytokinetic bridge; Mitotic spindle
Pathways (Reactome):
Metabolism: Synthesis of 12-eicosatetraenoic acid derivatives; Synthesis of 15-eicosatetraenoic acid derivatives; Synthesis of 5-eicosatetraenoic acids
Cellular responses to stimuli: Detoxification of Reactive Oxygen Species
Gene Ontology:
Molecular function: glutathione peroxidase activity; phospholipid-hydroperoxide glutathione peroxidase activity; electron transfer activity; peroxidase activity
Biological process: cellular response to oxidative stress; cellular oxidant detoxification; response to oxidative stress
Cellular component: cytosol; cytoplasm
Genetic constraint (gnomAD): Loss-of-function variants: 21 observed, 14.98 expected, observed/expected ratio (o/e) 1.4, 90% interval 0.99 to 1.88. The upper end of that interval is the gene's LOEUF score, 1.88, which puts it in group 6 of 6, group 1 being the genes least tolerant of losing a copy. Missense variants: 241 observed, 263 expected, observed/expected ratio (o/e) 0.92, 90% interval 0.82 to 1.02. Synonymous variants: 94 observed, 100.38 expected, observed/expected ratio (o/e) 0.94, 90% interval 0.79 to 1.11.
Homologues: Orthologues: macaque GPX2 (99% identical), dog GPX2 (97% identical), pig GPX2 (97% identical), rabbit GPX2 (95% identical), rat Gpx2 (94% identical), mouse Gpx2 (94% identical), chimpanzee GPX2 (79% identical), guinea pig GPX2 (74% identical), Caenorhabditis elegans gpx-3 (34% identical), Caenorhabditis elegans gpx-5 (33% identical), Caenorhabditis elegans gpx-2 (26% identical), Caenorhabditis elegans gpx-8 (20% identical), and 1 more. Paralogues in human: GPX1 (67% identical), GPX5 (46% identical), GPX3 (41% identical), GPX6 (40% identical), GPX4 (31% identical), GPX7 (28% identical), GPX8 (28% identical).
Diseases named in the same sentence as GPX2 in open-access papers:
GPX2 is named in the same sentence as 86 diseases in open-access papers, as found by Europe PMC text mining. Sharing a sentence is not in itself a finding about the gene and the disease. The quoted sentences say what the papers report.
colitis (20 papers, 2012 to 2025). Inflammation of the colon. "Further, Gpx1 activity is associated with enhanced Treg cell activity in mice, and mice deficient in both glutathione peroxidases, Gpx1 and Gpx2, develop spontaneous colitis." (PMID 23776564, 2013). "These novel findings are complemented by the demonstration of reduced GPx1 in the colon of mice with DSS-induced colitis, murine colitis induced by knockout of GPx1 and GPx2, and genome-wide association studies that note polymorphisms in antioxidant genes, including GPxs in IBD." (PMID 39695083, 2024). "Furthermore, GPx knockout mice for the widely expressed GPx1 and its epithelium-specific variant GPx2 develop intestinal inflammation and colitis." (PMID 35052541, 2021). "Meanwhile, broccoli sprouts and bok choy increased the expression of antioxidants such as Nrf2, NADH-Quinone oxidoreductase 1, Gstm1, Srxn1, and GPx2 to improve colitis symptoms." (PMID 38779039, 2024). "With the antioxidant function of selenoproteins that can play roles in intestinal inflammation, spontaneous colitis can be induced in GPx1 and GPx2 knockout mice." (PMID 35624837, 2022). "In view of the high activity of COX and LOX pathways during inflammatory bowel disease our data therefore provide new insights into the mechanisms of the protective function of GPx1 and GPx2 during colitis as well as inflammation-driven carcinogenesis." (PMID 31765890, 2020). "In the murine dextran sodium sulfate (DSS)-induced colitis model, GPx2 was specifically increased in cells near ulcerations which are involved in the regeneration of the epithelial layer." (PMID 31765890, 2020). "A murine colitis model showed that Gpx2 is upregulated via signal transducer and activator of transcription (STAT) not Rrf2." (PMID 28744337, 2017). "Increased GPX2 expression has also been shown in colitis, which is induced by signal transducers and activators of transcription (STAT) factors." (PMID 28744337, 2017). "In contrast, inflammatory diseases such as colitis develop spontaneously in GPx-1−/− × GPx-2−/− mice, suggesting that inflammation is augmented." (PMID 24743300, 2014). "Here, we demonstrate that unchallenged GPx2-KO mice have a low-grade colitis, characterized by increased spleen weight, infiltration of inflammatory cells, and crypt elongation." (PMID 23977205, 2013). "The pro-carcinogenic activity of GPx2 after AOM-treatment alone highlights the crucial impact of the DSS-colitis as a tumor-driving force in the AOM/DSS model." (PMID 23977205, 2013). "Mice deficient in both GPx1 and GPx2 spontaneously develop ileocolitis and DSS-induced colitis is more severe in mice deficient in GPx2." (PMID 23977205, 2013). "All AOM/DSS-treated mice developed colitis which was generally more severe in GPx2 KO mice than in WT mice under all Se states and especially high in moderate Se-deficiency." (PMID 22654914, 2012). "Surprisingly, it enhanced colitis in Se-poor WT and GPx2 KO mice but decreased it in Se-adequate mice to an identical score in both genotypes." (PMID 22654914, 2012). "In dextran sulfate sodium (DSS)-induced colitis, GPX2 expression is enhanced in both the acute and recovery phases of inflammation, driven by IL22–mediated activation of STAT3, a member of the STAT family of cytoplasmic transcription factors involved in cell proliferation, survival and oncogenesis." (PMID 41300456, 2025). "Accordingly, in a previous study in animals with DSS-induced colitis, Hiller and colleagues found that GPX2 was induced through activation of STAT3, a transcription factor involved in wound healing, proliferation, and protection from apoptosis during acute injury." (PMID 29881384, 2018). "GPx2 and GPx1 are important regulatory factors of epithelial cells and may affect inflammatory responses, and speculate that GPx1 and GPx2 have certain protective functions in colitis and inflammation-driven carcinogenesis." (PMID 35624837, 2022).
colitis (continued). "Indeed, GPx2 has been shown to be upregulated during intestinal inflammation, e.g., during the regeneration of the crypt epithelium after radiation-induced injury and during colitis both in humans and in mice." (PMID 31765890, 2020). "In contrast, GPx2-KO mice developed more tumors in an AOM/DSS-induced colon cancer model, which correlated with a more severe DSS-colitis upon GPx2 deletion." (PMID 23977205, 2013). "In the spleen, Nfe2l2, Gclc, Gsr, Sod2, Gpx1, Gpx2, and Prdx1 were not consistently affected by T cell transfer colitis." (PMID 31212794, 2019). "In the MLN, colitis also reduced the expression of Nrf2 (Nfe2l2), γ-glutamylcysteine synthetase (Gclc), glutathione reductase (Gsr), Gpx1, and Gpx2 by 27% to 45% relative to the non-colitic control." (PMID 31212794, 2019). "In addition, it has been found that probiotics such as Lactobacillus plantarum ZDY2013 and Bifidobacterium bifidum WBIN03 can regulate the secretion of antioxidant enzymes, SOD1, GPX2 and CAT, by activating the Nrf2 pathway, while achieving the effect of alleviating colitis." (PMID 35681318, 2022). "Moreover, LSE enhanced GPX1 and GPX2 levels in DSS-induced colitis mice, although it was not significant (P > 0.05)." (PMID 35059326, 2021).
breast carcinoma (17 papers, 2013 to 2025). "In fact, GPx2 downregulation is a physiologically relevant change in breast cancer; analysis of a database of 1,809 patients, showed an association of GPx2 mRNA downregulation in luminal B, HER2-enriched, and basal-like tumours with poor patient survival." (PMID 38238426, 2024). "Redox signaling caused by knockdown (KD) of Glutathione Peroxidase 2 (GPx2) in the PyMT mammary tumour model promotes metastasis via phenotypic and metabolic reprogramming." (PMID 38238426, 2024). "Our recent work highlights the profound effects of redox signalling by GPx2 KD on the mammary tumour phenotype involving ROS/HIF1α signalling, causing vascular malfunction, resulting in hypoxia and metabolic plasticity." (PMID 38238426, 2024). "Loss of the antioxidant glutathione peroxidase 2 in breast cancer cells increases reactive oxygen species, thereby activating hypoxia inducible factor-α (HIF1α) signaling." (PMID 35193955, 2022). "In sum, the cumulative data point to profound effects of GPx2 loss on mammary tumor progression, resulting in ROS/HIF1α/VEGFA signaling, causing vascular malfunction and hypoxia." (PMID 35193955, 2022). "Moreover, the loss of GPx2 in several molecular breast cancer (BC) subtypes was correlated with poor patient survival, underscoring the clinical significance of GPx2 loss in BC." (PMID 35193955, 2022). "Although elevated Gpx2 levels have been linked to increased breast cancer risk, Gpx2 may reduce the risk of breast cancer metastasis." (PMID 32731460, 2020). "ROC curve and survival analysis for GPXs family revealed that some of them might serve as promising diagnostic and prognostic biomarkers for breast cancer, especially GPX2 and GPX3." (PMID 32782436, 2020). "High GPx2 expression levels were associated with poorer prognosis in non-small cell lung cancer, glioblastoma, castration-resistant prostate cancer and nasopharyngeal carcinoma, while the opposite trend was observed in breast cancer, esophageal squamous cell carcinoma and bladder cancer." (PMID 37138031, 2023). "Moreover, GPx2 caused dramatic suppression of mammary tumor growth relative to control tumors." (PMID 35193955, 2022). "In our dataset, GPX2 was significantly overexpressed in breast cancer samples with BRCA1 promoter inactivation and identified as a hub gene, suggesting a potential role in tumor progression under BRCA1-deficient conditions." (PMID 40870889, 2025). "In breast cancer, it has been further shown that redox signaling by Glutathione Peroxidase 2 (GPx2) controls the EM plasticity, thus affecting the process of metastasis." (PMID 39124569, 2024). "We used single-cell transcriptomics to decipher the tumour cell subpopulations stimulated by GPx2 KD in the PyMT mammary tumour and paired pulmonary metastases." (PMID 38238426, 2024). "To identify the subpopulation(s) driving spontaneous metastasis, we performed scRNA-seq of lung metastases (mets) that were derived from the parent PyMT1/GPx2 KD mammary tumour." (PMID 38238426, 2024). "Analysis of all clusters in the GPx2 KD vs control mammary tumour in UMAPs unravelled a significant increase in the size (cell number) of cluster 3 from 683 (8.96%) in control to 983 (12.65%) in GPx2 KD tumour." (PMID 38238426, 2024). "scRNA-seq of FACS-sorted GFP-labelled cells from one PyMT1/GPx2 KD and one PyMT1/control mammary tumour unravelled seven carcinoma cell subpopulations (clusters) that were shared by the GPx2 KD and control tumour." (PMID 38238426, 2024). "The high expression of Gpx-2 was also detected in the case of gastric, oesophageal, liver and breast cancers." (PMID 37834097, 2023). "In search of redox mechanisms in breast cancer, we uncovered a striking role for glutathione peroxidase 2 (GPx2) in oncogenic signaling and patient survival." (PMID 35193955, 2022).
breast carcinoma (continued). "We performed scRNA-seq of GFP-labeled PyMT1/GPx2 KD and PyMT1 control cells, freshly isolated from one mammary tumor each." (PMID 35193955, 2022). "In breast cancer, GPx2 is commonly overexpressed in the mammary carcinomas of mouse models of breast cancer induced by carcinogens, which is consistent with its up-regulation in human breast cancer." (PMID 32571353, 2020). "All these findings together indicated that only GPX2 and GPX3 possessed significant diagnostic and prognostic values for breast cancer." (PMID 32782436, 2020). "Four GPXs family genes had the significant ability to distinguish breast cancer tissues from normal breast tissues, including GPX2, GPX3, GPX4 and GPX8." (PMID 32782436, 2020). "As expected, the inhibition of GPx2 expression by siRNA led to significant growth inhibition in both rat and human breast cancer cell lines." (PMID 32571353, 2020). "Due to its potential function in the occurrence and development of breast cancer, GPx2 is suggested as a potential target for the prevention and treatment of breast cancer." (PMID 32571353, 2020). "For example, the repression of glutathione peroxidase 2 (GPx2) in breast cancer may enhance cancer progression due to hypoxic signals, aberrant vascularization, and a metabolic switch to the aerobic glycolysis/oxidative phosphorylation (OXPHOS) axis." (PMID 39404411, 2024). "GPx2 plays considerable roles in the development, progression and maintenance of tumors, including those of lung cancer, pancreatic cancer, glioblastoma and breast cancer." (PMID 37138031, 2023). "Indeed, treatment of mice bearing PyMT1/GPx2 KD tumors with daily intraperitoneal injection of echinomycin for 21 d following tumor onset substantially reduced mammary tumor growth." (PMID 35193955, 2022). "Breast cancer patients with higher expression of GPX2, GPX3 or GPX5 had better prognosis." (PMID 32782436, 2020). "However, the current research on the relationship between GPx2 and breast cancer is limited and there are still many gaps in the research regarding its regulatory mechanisms." (PMID 32571353, 2020). "Using carcinoma cell lines derived from the PyMT mammary tumor model, we found a dramatic down-regulation of the antioxidant GPx2 in the highly metastatic PyMT2 relative to the weakly metastatic PyMT1 tumor cell line, which were representative of other cell lines derived from the same mammary tumor." (PMID 35193955, 2022). "Moreover, GPx2 OE dramatically inhibits mammary tumor growth and spontaneous lung metastasis." (PMID 35193955, 2022). "The GPX2 gene increased the sensitivity of cell lines to kahalide (for treating breast cancer) and also increased the tolerance of cell lines to cisplatin (for treating breast cancer, bladder cancer, esophageal cancer, and head and neck cancer) and arsenic trioxide (for treating leukemia)." (PMID 33706760, 2021). "Immunoblotting of mammary tumour chunks showed dramatic upregulation of HIF1α that was concomitant with increased VIM, SNAI1, TWIST and decreased E-CAD expression in GPx2 KD relative to control tumours." (PMID 38238426, 2024). "The results revealed that GPX1, GPX2, GPX3 and GPX4 protein levels were markedly decreased in breast cancer when compared with normal controls." (PMID 32782436, 2020). "Overexpression of GPx2 in the HER2-amplified JIMT1 cell line, which is GPx2 negative and brain-metastatic, suppressed mammary tumour growth, resulting in benign tumours with decreased VIM and increased E-CAD levels relative to control tumours." (PMID 38238426, 2024). "Furthermore, we tested the effect of GPx2 KD spontaneous lung colonization, 8 wk postremoval of similarly sized MDA-MB-361 control and GPx2 KD mammary tumors, to uncouple metastasis from tumor burden." (PMID 35193955, 2022).
breast carcinoma (continued). "A comparison of carcinoma cell lines derived from the polyoma middle T (PyMT) mammary tumor model unraveled a dramatic down-regulation of glutathione peroxidase 2 (GPx2) in metastatic relative to nonmetastatic cells from the parental tumor." (PMID 35193955, 2022). "We found that GPX2 and GPX3 were significantly downregulated in breast cancer." (PMID 32782436, 2020). "Moreover, GPx2 KD resulted in abnormal intratumoral vessels that were long and tortuous, which were consistent with HIF1α and VEGFA up-regulation in GPx2 KD in mammary tumors." (PMID 35193955, 2022). "However, we found that GPX2 was not significantly downregulated in breast cancer." (PMID 32782436, 2020). "Overall, considering both the CCLE and LINCS datasets, eight selenoproteins were overexpressed (DIO2, GPX1, GPX4, SELENOI, SELENON, SELENOS, TXNRD1 and TXNRD3) and five were down-expressed (DIO1, GPX2, GPX3, SELENOP and SELENOW) in TNBC compared to all other “non-TNBC” breast cancer subtypes." (PMID 35158912, 2022).